NOS2 (nitric oxide synthase 2)
Diseases named in the same sentence as NOS2 in open-access papers (continued):
Sharing a sentence is not in itself a finding about the gene and the disease.
tumor (continued). "Furthermore, blocking NO production in mice via genetic deletion of NOS2 (inducible NOS [iNOS]) inactivation function abolished NK cell responses that confirming the main positive role of NO to support IL-2-NK cells induction against tumor cells." (PMID 31457012, 2019). "We next sought to determine whether elevated NOS2 levels induce EMT/CSC phenotype in tumour cells." (PMID 28382931, 2017). "NOS2 (inducible nitric oxide synthase) have been proposed as a component of molecular profile of several tumors, including glioma, one of the most aggressive primary brain tumor featuring local cancer stem cells responsible for enhanced resistance to therapies and for tumor recurrence." (PMID 28424427, 2017). "The marginal increase in NOS2 immunoreactivity in tumor vessel endothelium, along with the increased expression of all three NOS isoforms in other cells in liver, were associated with a significant overexpression of ET-1 immunoreactivity in all tumor tissue cells." (PMID 23691268, 2013). "However, the 250KDa form of NOS2 showed an increase only in tumor tissue." (PMID 21489226, 2011). "Similarly, in our study, NOS2 was never detected by immunohistochemistry in all the tumours tested, thus suggesting that the loss of NOS1 expression was not counterbalanced by induction of NOS2 expression in tumour cells." (PMID 15150612, 2004). "Nitric oxide synthase 2 (NOS2) and cyclooxygenase 2 (COX2) tumor expression present significant obstacles for effective treatment of aggressive tumors including ER-negative breast cancer." (PMID 42097035, 2026). "Type 2: developing immune desserts lack stroma-restricted CD8+ T cells with tumor NOS2 and COX2 restricted to the tumor periphery." (PMID 42097035, 2026). "NOS2 and COX2 tumor expression shapes the immune landscape and mediates the transition from inflamed regions to immune deserts." (PMID 40663402, 2025). "A differential cluster distribution of the ratio of clustered populations by survival status (red and blue circles) revealed that deceased patient tumors had a greater percentage of distance-dependent NOS2+ and COX2+ tumor clusters." (PMID 40663402, 2025). "Together, these results show that tumor COX2 and NOS2 have key roles in the regulation of immune polarization, as well as mobility and infiltration of CD8+ T cells into the tumor core." (PMID 40663402, 2025). "Another study showed increased infiltration of both NOS2+ M1 and CD163+ M2 macrophages in the invasive tumor front (TF)." (PMID 40508145, 2025). "NOS2 expression is triggered by inflammatory cytokines (TNF-α and IFN-γ) and hypoxic conditions in the tumour microenvironment." (PMID 40567499, 2025). "While there was less difference between the control and Nos2– animals, inhibition of COX2 using the NSAID indomethacin resulted in extensive tumor infiltration of CD8+ TEff cells and a dramatic increase in IFN-γ." (PMID 40663402, 2025). "Multiple immune cell markers were evaluated, including T cell markers, CD3, CD4, CD8; the macrophage marker CD68; CK-SOX10 tumor marker; and immune modulatory factors, PD1, PDL1, FOXP3, IFN-γ, NOS2, and COX2." (PMID 40663402, 2025). "Patients with positive outcomes have low or sporadic tumor NOS2/COX2 expression and increased CD8+ TEff cells that penetrate deep into the tumor core." (PMID 40663402, 2025). "Cyclooxygenase-2 (COX-2) and nitric oxide synthase-2 (NOS-2), which contribute to immune suppression within TME, represent other markers whose tumor expression can be predictive of the level of immune response and/or outcome." (PMID 38892411, 2024). "The following observations support our finding: an increase in NOS2-positive M1 macrophages and a decrease in CD206-positive M2 macrophages in the tumor tissues of PyMTSB2−/− mice and the SerpinB2 knockdown RAW264.7 cells." (PMID 38956496, 2024).
tumor (continued). "Together, these spatially defined NOS2 and COX2 expression patterns shape the tumor immune microenvironment and identify cellular neighborhoods that promote cancer disease progression." (PMID 39356141, 2024). "On the other hand, in “immune-cold” areas of the tumor with low CD8+ T cells (immune deserts), there was notably less NOS2 and IFN-γ." (PMID 38892290, 2024). "M1 macrophages are tumor-resistant and can be identified by different phenotypic markers, including CD80/B7-1, CD86/B7-2, HLA-DR, and NOS2." (PMID 39599846, 2024). "Interestingly, tumor overexpression of IDO1 is associated with the amplified assembly of TAMs characterized by high expression of CD206, secretion of elevated levels of TGFβ, and a decrease in pro-inflammatory macrophages expressing NOS2, CD86, and IL-12 within the TME." (PMID 38185636, 2024). "Both NOS2 and COX2 promote drug resistance, metastasis, angiogenesis, and an immunosuppressive tumor microenvironment (TME)." (PMID 38912586, 2024). "In summary, inflammation in the tumor microenvironment (TME) and NOS2 and COX-2 co-expression play pivotal roles in the mechanisms driving unfavorable clinical outcomes." (PMID 38892290, 2024). "Spatial evaluation of NOS2 and COX-2 reveals orthogonal expression, suggesting the unique roles of these niches in the tumor microenvironment (TME)." (PMID 38892290, 2024). "The H&E, Ki67, TUNEL, DCFH‐DA, and GSH probe staining and IF staining with anti‐NOS2 antibody confirmed CAF remodel effects and tumor suppression of both primary and distant tumors." (PMID 38757665, 2024). "When interacting with tumor cells the mRNA expression of the M2‐like TAM marker, Arg1 was reduced, but the M1‐like TAM markers Nos2 and Ifn‐β were potentiated in the KO cells compared to the WT cells, which is consistent with the lactic acid treatment data." (PMID 38308188, 2024). "On the other hand, the optimal induction of NOS2 and COX2 in murine and human tumor cells requires IFNγ, and its combination with TNF-⍺ and IL-1β was more effective than with LPS." (PMID 38892290, 2024). "The direction of these changes was determined by analyzing the mRNA synthesis of specific factors (cytokines, Arg1, NOS2, Ido1) in TAS cells of tumor-bearing and other groups of the experimental mice." (PMID 38455363, 2024). "In contrast, tumors from surviving patients exhibited reduced NOS2 and COX2 clustering and increased CD8+ T-cell penetration into the tumor core." (PMID 39356141, 2024). "In particular, tumors with low expression of both NOS-2 and COX-2 showed a high infiltration of CD8+ T cells into the tumor core relative to tumors with elevated expression of these two markers." (PMID 38892411, 2024). "The immune desert is COX2+ but NOS2−; however, NOS2+ and COX2+ tumor satellites form in the inflamed areas near stroma-restricted CD8+ T cells that produce IFNγ." (PMID 39356141, 2024). "The combination of calycosin and formononetin decreased the expression of NOS2 in tumor tissues and cells and decreased TNF‐α production in the tumor area." (PMID 38230908, 2024). "Based on the comparison of M1- and M2-associated genes by RNA-Seq and qRT-PCR, we focused on validating the expression of NOS2 and CD206 in the tumor tissues." (PMID 38956496, 2024). "The treatment of HCC mouse tumor tissues with B. thetaiotaomicron and acetic acid resulted in upregulated expression of CD86 and NOS2, along with downregulated expression of CD163 and ARG1, as demonstrated by real-time PCR data and flow cytometry data." (PMID 38270111, 2024). "The requirement of IFN-γ and TNF-⍺/IL-1β for the upregulation of NOS2 and COX2 in human tumor cells implies that the microenvironment inducing NOS2-rich regions requires cells present that are releasing IFN-γ and other proinflammatory cytokines." (PMID 38892290, 2024).
tumor (continued). "Recently, elevated NOS2 and COX2 expression was discovered in distinct immune and tumor cells upon treatment with IFNγ and cytokines or TLR4 agonists, consistent with feedforward NOS2/COX2 signaling as previously reported." (PMID 37169743, 2023). "A potential linear relationship between tumor NOS2 and COX2 in these tumors was examined using Pearson’s correlation coefficient, which revealed linear correlations between NOS2 and COX2 expression at strong, moderate, and weak intensities." (PMID 37169743, 2023). "While COX2 expression was observed near NOS2-expressing cells in some regions, COX2+ cells were densely clustered in distinct areas deeper into the tumor core as well as in immune desert regions of the tumor." (PMID 37169743, 2023). "Multiplex spatial imaging revealed clusters of high NOS2 expressing cells proximal to areas of stroma-restricted CD8+ T cells that are known to produce IFNγ and suggest a small inflammatory niche at the tumor/stroma interface in these tumors." (PMID 37169743, 2023). "To explore these possibilities, herein, we show that Th1 cytokines effectively stimulate NOS2 and COX2 expression in tumor cells in vitro." (PMID 37169743, 2023). "Spatial distribution and density heatmap analyses of the whole tumor reveal distinct regions of NOS2, COX2, and CD8+ T cells where NOS2- and COX2-expressing cells were observed in separate neighborhoods." (PMID 37169743, 2023). "Areas enriched for CD8+ T cells and IFNγ are related to the juxtaposition of lymphoid and tumor cells within the TME, which results in high clustering of enhanced NOS2-expressing cells." (PMID 37169743, 2023). "Consistent with previous reports in murine tumors, high NOS2 expression requires IFNγ and TNFα/IL1, which exhibit a striking difference in cytokines produced during induction of murine macrophages and tumor cells." (PMID 37169743, 2023). "Nitric oxide (NO), a signaling molecule generated by the family of nitric oxide synthases (NOS1, NOS2, and NOS3), plays a plethora of physiological and pathophysiological roles in the human body and in tumor biology." (PMID 37511047, 2023). "While elevated tumor COX2 expression was also predictive of a poor outcome as defined by HR of 2.45 in ER- patients from the same cohort, elevated NOS2/COX2 coexpression was strongly predictive of poor outcome (HR 21)." (PMID 37169743, 2023). "High expression of TNF-α, IL-1β, NOS2 and CD86 implied the polarisation of HF-CAR-PMs inside HER2+ tumours toward M1 phenotype." (PMID 37386139, 2023). "Contrarily, NOS2+ and COX2+ cells are scattered and observed at lower levels in areas with increased CD8+ T cell penetration into the tumor." (PMID 37169743, 2023). "A strong correlation between NOS2 and COX2 tumor expression and poor clinical outcomes in ER breast cancer has been established." (PMID 37169743, 2023). "NOS2 and COX2 fluorescent intensities were determined for each tumor using real-time tuning in HALO software, and then mean intensities and standard deviations (SD) were determined." (PMID 37169743, 2023). "We directly challenged NOS2KO animals with tumors to evaluate the effects of their specific deletion of Nos2 in the entire T-cell compartment (encompassing CD8+ and CD4+ T cells) on tumor growth." (PMID 36574610, 2023). "Further examination of NOS2 and COX2 spatial distributions revealed that NOS2+ cells are clustered at tumor margins or in the stroma." (PMID 37169743, 2023). "Administration of exoASO-STAT6 leads to induction of nitric oxide synthase 2 (NOS2), an M1 macrophage marker, resulting in remodeling of the tumor microenvironment and generation of a CD8 T cell–mediated adaptive immune response." (PMID 35179953, 2022). "Seventy-five percent of the genes that were differentially expressed between spleen and tumor MDSCs were common to both subtypes, including the classical tumor MDSC markers Arg1 (>100-fold increased) and Nos2 (16- to 32-fold increased)." (PMID 36480485, 2022).
tumor (continued). "Fourth, the high expression levels of IFN-γ,IL-12, and Nos2 and low expression levels of TGF-β, IL-10, andArg-1 in the tumor tissue confirmed that a strong tumor-specific immuneresponse had been elicited." (PMID 35926215, 2022). "In contrast, TLR4, NOS2, IL-6, MIP-3α, and VEGF were highly expressed in the transplanted tumour tissues from the LPS groups, and their expression levels were decreased in the TLR4-silenced groups." (PMID 36010574, 2022). "After adjusting for tumour purity, there was a correlation between CD44 outside CD8B and NOS2 and most of the immune markers." (PMID 36316684, 2022). "For example, in hepatocellular carcinoma, iNOS (NOS2) overexpression in cancer cell lines and human tissues promotes NOTCH-1-mediated stemness and tumor initiation in vivo, through a cGMP/PKG dependent mechanism." (PMID 35740092, 2022). "The Q-PCR results from all the tumors of each treatment group showed that several chemokines and cytokines were positively correlated with tumor size, including IL-4a, IL-6, IL-10, CSF-1, CSF-2, INF-r, and NOS-2." (PMID 35058524, 2022). "CD40/CD40L signaling strengthens Nitric oxide synthase 2 (NOS2) expression, and production of nitric oxide and TNF-α through CD40 contributes to tumor elimination by adoptive cell transfer." (PMID 35806328, 2022). "Western blotting results showed that NOS2 and ALOXE3 expression was significantly increased in tumor tissues compared with that in normal tissues (P < 0.01)." (PMID 35265525, 2022). "Since arginase-1 (ARG-1) and nitric oxide synthase 2 (NOS2) activation leads to the suppressive effects of MDSCs, we next checked the expression of ARG1 and NOS2 in the tumor collected from the treatment groups." (PMID 34381456, 2021). "Inhibitors of NOS2 and COX2 block the proteins’ activities, interrupt the feed-forward loop, and reduce tumor growth rate." (PMID 33859337, 2021). "Especially in the tumor tissue of LUAD, both IRF5 and NOS2 show significant correlations with LPAR6 expression and PTGS2 shows a significant correlation with LPAR6 expression in the tumor tissue." (PMID 34769557, 2021). "Two enzymes participating to arginine-metabolism NOS2 and ARG1 are up-regulated in tumor specimens where act as key mediators for T cell suppressive mechanisms." (PMID 34675917, 2021). "Three isozymes of NOSs: neuronal NOS (NOS1), inducible NOS (NOS2), and endothelial NOS (NOS3), all contribute to tumor progression through distinct effects of biological regulation on tumorigenesis." (PMID 33859186, 2021). "Previous data suggested that co-expression of NOS2 and COX2 is a strong prognostic indicator in TNBC patients, also contributing to tumor aggressiveness and poor patient prognosis." (PMID 32423132, 2020). "Tumor-adjacent tissue had higher expression of ARG1, DDAH1, and DDAH2 and lower NOS2 than patients-matched tumors." (PMID 32932854, 2020). "In tumor-bearing mice, the inhibition of SETD1B suppressed the H3K4me3 level at the Nos2 promoter region and diminished the inducible nitric oxide synthase expression in myeloid-derived suppressor cells." (PMID 32636801, 2020). "Gene expression analyses performed on CD11b+ tumor infiltrating immune cells isolated from EONY#17 tumors showed enhanced expression of the M1-like markers IL1β, Cxcl9, IL6 and Nos2." (PMID 31519152, 2019). "In this context, all the inhibitors already used in therapeutic schemes to block IDO, HO, ARGI and II, NOS2, PGE2, and TGF-β activity can be employed to reduce MSC influence on tumor cell growth." (PMID 29515580, 2018). "Treatment of tumour cells with DPTA resulted in increased tumour cell invasion, however, blockade of NOS2 by 1400 W suppressed the mMDSC mediated tumour cell invasion." (PMID 28382931, 2017). "To show that NOS2 is functionally important in PDAC tumor cells we evaluated the drug response data of the CCLE and found that multiple drugs are more or less effective depending on the expression of NOS2." (PMID 27762323, 2016).
tumor (continued). "Nitric oxide synthase 2 (NOS2) is the inducible form of these enzymes and its expression is found in various cell types such as myeloid, stromal and tumor cells." (PMID 27812136, 2016). "We therefore further examined different macrophage markers (M1; Nitric oxide synthase 2 (NOS2) and M2; CD163 and Heme oxygenase 1 (HMOX1)) in prostates injected with the different tumor EVs." (PMID 27550147, 2016). "NOS2 and CD163 expression at the tumor invasive front in relation to molecular characteristics in CRC." (PMID 23077543, 2012). "The majority of NOS2 and CD163 expression was found in cells located in the tumor stroma, with the highest density along the invasive tumor front." (PMID 23077543, 2012). "Because of the strong correlation between tumor stage and the expression of NOS2 and CD163 we performed multivariate Cox proportional hazard models including the variables gender, age, localization, tumor stage, and one macrophage marker, respectively." (PMID 23077543, 2012). "The average infiltration of NOS2 and CD163 expressing macrophages along the invasive tumor front was semi-quantitatively evaluated using a four-graded scale." (PMID 23077543, 2012). "After adjustment for age at diagnosis, tumor ER status, and TNM stage, an OR of 4.5 described the significant relationship between NOS2 and phosphorylated Akt at ser473 in these tumors." (PMID 22957045, 2012). "NOS2 and CD163 expression at the tumor invasive front in relation to clinicopathologic characteristics in CRC." (PMID 23077543, 2012). "Expression of NOS2 and CD163 inversely correlated to tumor stage, indicating that higher stage tumors to a larger extent have escaped the immune system." (PMID 23077543, 2012). "By day 7, IFNγ, CSF2, CXCL10, GZMB, PTGS2, TNFα, CD80, CCL22, IL12a, IL13, IL1b, IL6, NOS2, and CTLA4 were significantly upregulated in the tumor-bearing mice bladders and AGTR2 and GATA3 were downregulated." (PMID 22013484, 2011). "A panel of selected representative pro-inflammatory genes (RAGE and P2X7R, COX2, NOS2 and, PTX3) were analyzed, comparing tumor, peritumor and host normal tissues." (PMID 21489226, 2011). "The inhibitory activity of IL13, IL1b, PTGS2, NOS2, and CTLA4 on the immune response would enhance tumor growth." (PMID 22013484, 2011). "LMM3 cells express COX-1, COX-2, NOS2, NOS3 and arginase II, involved in angiogenesis and tumor cell migration." (PMID 18261208, 2008). "Because NOS2 and COX2 promote cytokine release and activation of IL-10 and TGF-β, NOS2 and COX2 tumor expression could complement one another regionally to maintain immune suppression." (PMID 40663402, 2025). "In paired primary–metastasis cohorts, NOS2 expression was lower in metastases; in experimental models, manipulating NOS2 in tumor cells did not robustly drive metastasis, suggesting context dependence." (PMID 41268067, 2025). "Different subsets of immunosuppressive TAMs (SPP1-C1Qa/b, proliferating, Nos2 glycolytic and OXPHOS TAMs) exhibited high expression of Trem2, Axl, Tim3 and Arg1, known markers of a pro-tumor phenotype, and were proportionally decreased in response to ACTM-838 treatment (except OXPHOS TAMs)." (PMID 41048107, 2025). "Remarkably similar changes were observed in the 4T1 model, where systemic NOS2 depletion and indomethacin treatment led to increased CD8+ T cell infiltration, N1 neutrophils, and active B cells, which translated to increased cures in 4T1 tumor-bearing mice." (PMID 40663402, 2025). "One study suggests that reducing NOS2 expression alters the spatial orientation and density of lymphoid cells, particularly CD8 T cells within the tumor microenvironment and when NOS2 is depleted and COX2 is inhibited, tumor growth slows and the immune response enhances." (PMID 40642105, 2025). "Notably, NOS2 and ARG1 are expressed not only by tumor cells but also by immune cells that infiltrate the TME." (PMID 41573553, 2025).